Y_RNA (Y RNA )
Gene: Miscellaneous RNA gene on chromosome 1 (202,914,880 to 202,914,980, reverse strand). Ensembl gene ENSG00000199471.
Homologues: Orthologues: chimpanzee Y_RNA (97% identical), macaque Y_RNA (93% identical). Paralogues in human: Y_RNA (85% identical), RNY3 (84% identical), Y_RNA (84% identical), Y_RNA (83% identical), RNY3P1 (82% identical), Y_RNA (82% identical), Y_RNA (81% identical), Y_RNA (80% identical), RNY3P11 (79% identical), Y_RNA (79% identical), RNY3P16 (78% identical), Y_RNA (78% identical), and 93 more.